NCOA7 (nuclear receptor coactivator 7)
Diseases named in the same sentence as NCOA7 in open-access papers (continued):
Sharing a sentence is not in itself a finding about the gene and the disease.
influenza infection (1 paper, 2025). "We found that the resistance of H820 cells to influenza infection is likely linked to impaired viral entry—due to high basal levels of interferon-induced proteins known to inhibit endocytosis (IFITM1/2/3, NCOA7, and CH25H)—and to increased expression of mRNAs that encode other antiviral factors." (PMID 40434103, 2025).
kidney cancer (1 paper, 2025). Primary or metastatic malignant neoplasm involving the kidney. "The schematic illustrates that NCOA7 upregulation interacts with V-ATPase to promote autophagosome-lysosome fusion, enhance autophagic degradation of lipid droplets, and thereby suppress proliferation, migration, and invasion of kidney cancer cells." (PMID 41120258, 2025).
renal carcinoma (1 paper, 2025). A carcinoma arising from the epithelium of the renal parenchyma or the renal pelvis. "Bioinformatics analysis showed that NCOA7 was expressed at low levels in renal cancer tissues and independently associated with the prognosis in patients with renal cancer." (PMID 41120258, 2025). "In vitro experiments showed that high NCOA7 expression inhibited the proliferation, migration, and invasion of renal cancer cells." (PMID 41120258, 2025). "Our study demonstrates that NCOA7 promotes autophagy and reduces lipid accumulation by binding to V-ATPase and ultimately inhibits the progression of renal cancer." (PMID 41120258, 2025). "This study aimed to investigate the role of nuclear receptor co-activator 7 (NCOA7)-mediated autophagy in lipid metabolism in renal cancer and its effects on renal cancer progression." (PMID 41120258, 2025). "High expression of NCOA7 enhanced autophagy and lipid metabolism and inhibited the growth of renal cancer cells." (PMID 41120258, 2025). "Additionally, NCOA7 expression was modulated in renal cancer cell lines transfected with LC3 dual-fluorescent virus to study its effects on lysosomal function, autophagy, and lipid metabolism." (PMID 41120258, 2025).
renal cell carcinoma (1 paper, 2023). "NCOA7 expression was downregulated in all three subtypes of renal cell carcinoma, and only had significant prognostic value for patients with ccRCC." (PMID 37511343, 2023). "Bioinformatic analysis identified the prognostic significance of NCOA7, but only for ccRCC, a subtype of renal cell carcinoma." (PMID 37511343, 2023).
tumor (11 papers, 2007 to 2025). "This study aims to evaluate the radiogenomic features associated with NCOA7 low expression in ccRCC patients and its correlation with tumor aggressiveness." (PMID 40282346, 2025). "Radiogenomic characteristics associated with NCOA7 expression in ccRCC reflect the aggressive nature of the tumor." (PMID 40282346, 2025). "Including patients from diverse geographic locations and healthcare settings would allow for the identification of potential variations in NCOA7 expression patterns and their associations with tumor aggressiveness and clinical outcomes." (PMID 40282346, 2025). "The expression of NCOA7 was positively associated with tumor size (T-stage; P=0.005) and lymph node metastasis (N-stage; P=0.008)." (PMID 38699661, 2024). "The expression of NCOA7 was positively associated with the tumor size (P=0.020), T-stage (P=0.005) and N-stage (P=0.008)." (PMID 38699661, 2024). "Moreover, functional studies are essential to investigate the molecular mechanisms underlying the role of NCOA7 in tumor biology." (PMID 40282346, 2025). "Additionally, the expression level of NCOA7 was negatively correlated with the tumor mutation burden (p < 0.001)." (PMID 37511343, 2023). "Furthermore, we checked the NCOA7 expression in the TCGA dataset and found NCOA7 increased expression in the tumor samples and low-risk group had a larger NCOA7 expression than high-risk group." (PMID 36229806, 2022). "Because NCOA7 is often overexpressed and/or mutated in tumor microenvironments, our current data may provide evidence for a new immune check-point mechanism based on Trp metabolism and AhR." (PMID 31481962, 2019). "In conclusion, future research should focus on validating current findings in larger cohorts, exploring the mechanistic basis of NCOA7’s role in tumor biology, and developing practical applications in diagnosis and treatment." (PMID 40282346, 2025). "Significant differences in clinicopathological and CT-based tumor features were observed based on NCOA7 expression." (PMID 40282346, 2025). "NCOA7 low expression shares ill-defined margins and tumor necrosis, while primary tumor size is at the threshold of statistical significance." (PMID 40282346, 2025). "While our study highlights the association between low NCOA7 expression and aggressive radiological and clinical features, it remains crucial to elucidate the biological pathways through which NCOA7 modulates tumor behavior." (PMID 40282346, 2025). "Consistent with this study, we observed higher tumor grade and more advanced tumor stage according to the AJCC in ccRCC patients with NCOA7 low expression." (PMID 40282346, 2025). "This study identified an inverse relationship between NCOA7 expression and the tumor N and M stages, indicating that NCOA7 plays a role in suppressing the invasion and migration of ccRCC cells." (PMID 40282346, 2025). "By suppressing tumor growth and metastasis through the mitogen-activated protein kinase/extracellular signal-regulated kinase pathway, NCOA7 emerges as a promising prognostic marker and potential therapeutic target for ccRCC." (PMID 40282346, 2025). "NCOA7 inhibits tumor growth and metastasis of ccRCC through the MAPK/ERK pathway, thus indicating its potential as a prognostic marker and therapeutic target for ccRCC." (PMID 37511343, 2023). "In another study, NCOA7 promoted tumor cell proliferation via enhancement of AhR transcriptional activity in the absence of externally added ligands, possibly suggesting that NCOA7 is a ligand-independent coactivator of AhR." (PMID 31481962, 2019). "Two genes, NCOA7 and B2M, showed a similar expression level in tumor and bronchus (0.7 and 1.6 respectively)." (PMID 17697374, 2007). "Considering its role in suppressing tumor progression, therapies aimed at enhancing NCOA7 expression or mimicking its function could provide new therapeutic options." (PMID 40282346, 2025). "When the tumor was at a higher grading stage, the expression of NCOA7 was lower." (PMID 37511343, 2023).
tumor (continued). "In HER2− tumours, baseline expression of 48 genes associated with poor antiproliferative response (p < 0.005) including PERP and YWHAQ, the two most significant, and the transcription co-regulators (SAP130, HDAC4, and NCOA7) which were among the top 16 most significant." (PMID 31892336, 2019). "The radiogenomic characteristics of NCOA7 low expression share common features with Prolyl 4-Hydroxylase Subunit α 3 (P4HA3), specifically ill-defined margins and a more advanced tumor stage according to the AJCC." (PMID 40282346, 2025). "We showed that expression of NCOA7 was elevated in OSCC tissues, and was correlated with tumor location, tumor histological differentiation or lymph node metastasis." (PMID 27509054, 2016). "The present study revealed a negative correlation between the expression of NCOA7 and the tumor N and M stages, thus suggesting that NCOA7 inhibits the invasion and migration of ccRCC cells." (PMID 37511343, 2023). "However, P4HA3 also exhibits traits such as larger primary tumor size and signs of infiltration, which are not observed in NCOA7 low expression." (PMID 40282346, 2025). "Of them, expression of NCOA7 was found to be up-regulated in OSCC tissues by immunohistochemistry staining and western blotting, and correlated with a pan of clinicopathologic parameters, including lesion site, tumor differentiation status and lymph node metastasis." (PMID 27509054, 2016).
cancer (6 papers, 2016 to 2023). A tumor composed of atypical neoplastic, often pleomorphic cells that invade other tissues. "These interactions are likely to prove significant in the development of anti-cancer agents, as NCOA7 expression is abnormal in several types of tumors and their micro- environments." (PMID 37296860, 2023). "Considering that the accelerated cell cycle progression and unlimited cell proliferation are hallmarks of cancer cells, NCOA7 was selected for further studies." (PMID 27509054, 2016). "NCOA7 is a nuclear receptor coactivator that is downregulated in a variety of cancers." (PMID 37511343, 2023). "Hence, NCOA7 holds significant importance for targeted immunotherapy in cancer." (PMID 37511343, 2023). "An inhibitor of NCOA7 could represent a potential cancer checkpoint target." (PMID 37296860, 2023). "hsa-miR-342-3p was negatively correlated with downregulated gene targets such as ZNF462 and NCOA7, and hsa-let-7b/c were anti-correlated with predicted targets KRT5 and GABBR2, with known activities in the cancer pathways." (PMID 32182819, 2020). "Furthermore, we illustrated the expression of pyroptosis immune regulators across another∼10000 samples and revealed that CNST, GDF10, KCNC2, NAP1L2, NCOA7, and LINC00641 also revealed higher expression in cancer cells." (PMID 35620284, 2022).
infection (6 papers, 2019 to 2025). The state of being infected such as from the introduction of a foreign agent such as serum, vaccine, antigenic substance or organism. "We further show that presence of the polybasic furin cleavage site in SARS-CoV-2 Spike sensitizes infection to the inhibitory consequences of aberrant endosomal acidification by NCOA7." (PMID 34807954, 2021). "Next we examined the effect of TMPRSS2 on NCOA7-mediated inhibition of SARS-CoV-2 Spike pseudotype infection." (PMID 34807954, 2021). "Here, we used ectopic expression and gene knockout to demonstrate that NCOA7 inhibits infection by SARS-CoV-2 as well as by lentivirus particles pseudotyped with SARS-CoV-2 Spike in lung epithelial cells." (PMID 34807954, 2021). "To support our observation that TMPRSS2 can rescue infection from the suppressive effects of NCOA7 mediated endosomal acidification, we pharmacologically manipulated endosomal acidification and endo-lysosomal proteases." (PMID 34807954, 2021). "Conversely, infections with pseudotypes bearing wild-type or PRRA containing SARS-CoV-1 Spike revealed that addition of the polybasic furin cleavage site enhanced the inhibitory effect of NCOA7 from 2- to 4-fold." (PMID 34807954, 2021). "As previously shown, infection with the MLV pseudotype, where entry depends on macropinocytosis, was unaffected by NCOA7 expression." (PMID 34807954, 2021). "In addition, expression of the protein-coding genes CXCL10, IFIT1, NCOA7, IFIT2, SIX3, and RPSA was increased during infection." (PMID 40510596, 2025). "Like NCOA7, BafA1, E64d or Niclosamide treatment potently inhibited infection with Spike pseudotype in the absence of TMPRSS2, however, TMPRSS2 overexpression attenuated the inhibitory effects of each of these inhibitors." (PMID 34807954, 2021). "In the absence of TMPRSS2, NCOA7 inhibited infection by ~8-fold, however, in TMPRSS2 expressing cells the inhibitory effect dropped to ~3-fold." (PMID 34807954, 2021). "Consistent with all of the HCoVs being able to enter cells via the endocytic pathway, we found that NCOA7 inhibited infection by SARS-CoV-1, MERS-CoV, HCoV-229E and HCoV-NL63 Spike pseudotypes, demonstrating the pan-coronavirus antiviral activity of NCOA7." (PMID 34807954, 2021).
neurological diseases (2 papers, 2021 to 2023). "It has been reported that loss of function of OXR1, NCOA7, and TBC1D24 is associated with neurological diseases, including ASD, characterized by aberrant neurodevelopment." (PMID 37958785, 2023).
NCOA7 also shares sentences with these, for which no sentence is quoted: Ataxia (1 paper); autoimmune disease (1); bladder carcinoma (1); colon cancer (1); intellectual disabilities (1); kidney chromophobe (1); lung carcinoma (1); ovarian failure (1); Parkinson disease (1); pulmonary arterial hypertension (1); triple-negative breast carcinoma (1).